GLP1R (glucagon like peptide 1 receptor)
Diseases named in the same sentence as GLP1R in open-access papers (continued):
Sharing a sentence is not in itself a finding about the gene and the disease.
Obesity (continued). "As outlined in this review, recent clinical trials of advanced therapeutic candidates, including GLP-1R agonists, have provided hope that breakthrough pharmacological obesity treatments may be possible." (PMID 36834794, 2023). "Our research suggests that 10-HDA might represent an intervention nutrient that can deal with AD, DM, and obesity by targeting GLP-1R." (PMID 37623897, 2023). "In addition, GLP1R agonists have been approved for the treatment of obesity due to their suppressive effects on appetite and food intake." (PMID 37379656, 2023). "Obesity decreases the efficiency of GLP1R agonists in reducing food intake and body weight." (PMID 37293487, 2023). "Small short-term clinical trials have shown that the FDA-approved anti-obesity glucagon-like peptide-1 receptor agonists (GLP-1 RAs) improve insulin resistance in PCOS patients and may be superior to metformin." (PMID 36875461, 2023). "Recently, the gastric inhibitory polypeptide receptor/GLP1R (GIPR/GLP1R) co-agonist, tirzepatide, became the first polyagonist approved for the treatment of T2DM; it induces a staggering 22% average weight loss in patients with obesity." (PMID 36719381, 2023). "Importantly, we also provide a strategy to augment the therapeutic profile of the current frontline treatment for human obesity, GLP-1R agonists, via combination with 5-HT2CR agonists." (PMID 36592795, 2023). "In recent weeks, sections of the press, social media, and celebrities have been gushing in their praise of a new class of drugs for the treatment of obesity (known as Glucagon Like Peptide-1 Receptor Agonist [GLP-1 RA] eg, Semaglutide with the brand name Wegovy)." (PMID 37276026, 2023). "Elucidating the mechanisms through which GLP-1R agonists regulate body weight could enhance the therapeutic potential of these compounds or identify novel targets for anti-obesity drug development." (PMID 37930356, 2023). "Still, whether palatable food intake before or during the early development of obesity reduces the effects of GLP1R agonists on food intake and adipose tissue metabolism remains undetermined." (PMID 37293487, 2023). "Overall, whether exposure to an obesogenic environment before the onset or during early stages of obesity can reduce the anorectic effects of the central or peripheral administration of GLP1R agonists remains unclear." (PMID 37293487, 2023). "First, we examined whether different schedules of access during early exposure to a CAF diet before the onset of obesity reduced the anorectic effects of GLP1R activation by ICV and intraperitoneal (IP) EX4 administration." (PMID 37293487, 2023). "PCOS treatments may target the GLP-1R as the “anchor pharmacophore”, and there is emerging evidence for using tirzepatide to manage obesity and insulin resistance." (PMID 37510690, 2023). "A GLP-1R agonist, liraglutide, has been approved for obesity treatment." (PMID 37623897, 2023). "However, the mechanism of GLP-1R in treating obesity is still uncertain, and more clinical evidence is needed for its long-term safety and efficacy." (PMID 36843578, 2023). "The GLP-1R agonists are promising candidates for the treatment of obesity." (PMID 36843578, 2023). "Although a study has revealed a significant association between GLP-1R rs2268641 and obesity among European Americans, the available data do not provide conclusive evidence on how rs2268641 affects GLP-1R expression and function." (PMID 38096145, 2023). "This review describes evidence from previous research on the effects of GLP-1R agonists on obesity." (PMID 36843578, 2023). "Glucagon-like peptide-1 receptor agonists may therefore represent an important novel therapeutic option for treatment of HFpEF, especially when obesity-related." (PMID 38094687, 2023). "We first tested whether different schedules of CAF diet before the onset of obesity could reduce the anorectic, lipolytic, and thermogenic effects of GLP1R activation by peripheral and central EX4 administration." (PMID 37293487, 2023).
Obesity (continued). "We searched PubMed on 28 June 2021 for articles published in the past 5 years, with no language restrictions, using the search terms “cardiometabolic”, “cardiovascular”, “C-reactive protein”, “inflamm∗”, “glucagon-like peptide-1 receptor agonist”, “obesity”, and “overweight”." (PMID 36467859, 2022). "Interestingly, double incretin receptor knockout (DIRKO) and glucagon‐like peptide‐1 (GLP‐1) receptor KO mice (Glp1r‐/‐) also showed resistance to diet‐induced obesity, despite a significant increase in food intake in the GLP‐1 receptor KO mice." (PMID 35710141, 2022). "Given recent clinical findings and evidences, in this context glucagon-like peptide-1 receptor agonist is currently available as a candidate that is clinically positioned as a first-line anti-obesity agent for the effective prevention of ORCVDs in people with obesity." (PMID 36068534, 2022). "Given that some GLP-1 analogs are FDA-approved drugs to treat obesity, they may function via these widespread GLP-1R-expressing neurons." (PMID 36309763, 2022). "In addition to bringing glucoregulatory benefit,the GLP-1 receptor (GLP-1R) agonist (GLP1-RA) drug class has recently been licensedfor the treatment of obesity, owing to the anorexigenic properties of GLP-1Rengagement in the CNS." (PMID 35430298, 2022). "Targeted exome sequencing of six genes encoding drug targets for obesity or T2DM in 11,806 individuals with well-defined metabolic traits, followed by targeted genotyping of 39,979 individuals, reported an association of GLP1R rs10305492 (Ala316Thr) with lower fasting glucose and T2D risk." (PMID 35408810, 2022). "Background and Objectives: This study aimed to investigate the changes in obesity severity, glucose metabolism, and body composition in patients with obesity and type 2 diabetes mellitus treated with glucagon-like peptide 1 receptor agonist (GLP1-RA) semaglutide." (PMID 36135828, 2022). "The GLP‐1R agonist liraglutide has been shown to reduce bodyweight in patients with prediabetes and in those with obesity, and has been approved for weight management in adults with obesity as an adjunct to a reduced‐calorie diet and increased physical activity." (PMID 34713962, 2022). "In addition, results from the STEP 3 trial demonstrate that the GLP‐1R agonist semaglutide reduces bodyweight in adults with obesity." (PMID 34713962, 2022). "In addition, our previous studies demonstrated that GLP‐1R activation was sufficient to attenuate pressure overload‐, obesity‐, and sepsis‐induced cardiac dysfunction." (PMID 35166002, 2022). "Several studies investigated GLP1R polymorphisms in relation to the pathogenesis of obesity and T2DM; however, the results were not consistent among studies." (PMID 35408810, 2022). "However, recent studies have shown that GIPR-GLP1R co-agonists or GIPR-GLP1R unimolecular agonists are unexpectedly more effective anti-hyperglycemic and anti-obesity agents compared to GLP1R agonist control." (PMID 34911028, 2021). "For instance, obesity is characterized by greater insula responsiveness to food cues relative to normal weight individuals and this difference is abolished by acute treatment with the GLP-1R agonist exenatide." (PMID 33803053, 2021). "Interestingly, the Sisley group generated mice with glutamatergic neuronal deletion of GLP-1R and observed that GLP-1R agonists successfully execute glucose-lowering effects but fail to induce weight loss, suggesting that the brain may control the anti-obesity actions of GLP-1." (PMID 34869379, 2021). "As alluded to above, the ability of OXM to effectively activate both GCGR and GLP-1R, thereby improving blood glucose and body weight, is attractive for the development of peptide therapeutics for obesity/T2DM, provided an appropriate receptor balance is struck." (PMID 34093449, 2021).
Obesity (continued). "GLP-1R/GCGR co-agonists may hold advantages over GLP-1R mono-agonists for treating obesity and related metabolic diseases as their GCGR-mediated effects on energy expenditure can promote additional weight loss." (PMID 33933675, 2021). "Similarly, chemogenetic activation of PPG neurons led to reduced food intake and metabolic rate, and depletion of PVH GLP-1R resulted in increased food intake and obesity." (PMID 33206596, 2020). "In this paper, we therefore study the effects of GSPE on intestinal GLP-1R at a dose previously shown to have long-lasting anti-obesity activity and analyze whether GSPE exerts an epigenetic modulation." (PMID 31842341, 2019). "However, the specific function and underlying mechanisms of GLP-1R in COPD and in MS (possible obesity) remain uncertain." (PMID 30836679, 2019). "Here, we examine how a dose of grape seed proanthocyanidin extract (GSPE) with anti-obesity activity affects intestinal GLP-1R and analyze whether epigenetics play a role in the long-lasting effects of GSPE." (PMID 31842341, 2019). "In this view, glucagon-like peptide-1 receptor agonists (GLP-1 RAs), by providing an additional benefit of weight loss, would represent a preferable second-line option for patients with obesity and inadequately controlled diabetes, as adjunct to lifestyle interventions and metformin." (PMID 31892206, 2019). "Multiple GLP-1R co-agonists are emerging for the treatment of obesity and diabetes." (PMID 30459715, 2018). "However, the clinical applicability of GLP-1R analogs to reverse obesity and improve metabolic rearrangements is suboptimal and associated with dose-limiting adverse gastrointestinal events." (PMID 25652173, 2015). "Based on the positive correlations between both HbA1c and BMI and DNA methylation of CpG site −376, the present study suggests that hyperglycaemia and/or obesity may affect DNA methylation of GLP1R in human islets." (PMID 23879380, 2013). "This article reviews how the molecular evolution of GLP-1 and GLP1R contributes to the selective interaction between this ligand-receptor pair, providing critical clues for the development of potent agonists for the treatment of diabetes mellitus and obesity." (PMID 23181056, 2012). "Hence, GLP-1R agonists represent a promising class of new drugs with dual anti-obesity and anti-diabetic properties." (PMID 21151924, 2010). "Global GLP-1R–knockout mice have normal bodyweight, normal food intake on a standard chow diet, and are protected from, rather than more susceptible to, high-fat diet–induced obesity." (PMID 41542773, 2026). "In addition to controlling glucose homeostasis, some GLP-1R therapies are used to treat obesity." (PMID 41178720, 2025). "Although GLP-1R expression in peripheral tissues is generally low and restricted to rare cell types, antiinflammatory benefits have been observed in various preclinical models, such as obesity, atherosclerosis, steatohepatitis, and nephritis, even in the absence of direct immune cell targeting." (PMID 41178710, 2025). "It is possible that with the expansion of GLP-1 medications—glucagon-like peptide-1 receptor agonists, a class of drugs used to treat type 2 diabetes and, in some cases, moderate-to-severe obesity—we might see a notable change in BMI at the population level with time." (PMID 40573086, 2025). "In the SURPASS-2 trial, patients with obesity and T2D who received tirzeapatide (5 mg weekly) achieved greater HbA1c and body weight reductions than those receiving semaglutide (1 mg weekly) during the 40 week study despite comparable putative GLP-1R occupancy at these doses." (PMID 39963285, 2025). "The potential emerging pharmacological treatments for metabolic syndrome, especially for obesity and DM with glucagon-like peptide-1 receptor agonists (GLP1A), might promise a secure way for prevention of bone formation in this context, a hypothesis that should be further explored." (PMID 41515603, 2025).
Obesity (continued). "Finally, further high-throughput investigations to evaluate all other key residues involved in GLP-1R-cholesterol binding will generate high value data for the future development of novel GLP-1R allosteric modulators with improved signalling properties for the treatment of T2D and obesity." (PMID 40270220, 2025). "However, disease states (e.g., obesity, Cushing’s syndrome, type 1 diabetes [T1D] and anorexia nervosa) and some commonly used drugs [e.g., glucocorticoids and glucagon-like peptide 1 receptor agonists (GLP-1RAs)] that impact pancreatic β-cell insulin secretion can also alter the GH/IGF-I axis." (PMID 39665021, 2024). "However, the use of glucagon-like peptide 1 receptor agonists (GLP-1 RAs) is promoting the belief that drug-based management of obesity may be possible for long-term treatment with suitable tolerability and safety." (PMID 38807146, 2024). "Liraglutide (Saxenda) and semaglutide (Wegovy) are GLP‐1R agonists approved by the United States Food and Drug Administration for obesity treatment in 2014 and 2021, promoting the belief that breakthrough, drug‐based management of obesity may be possible." (PMID 38812572, 2024). "In addition, researchers have found out that glucagon-like peptide-1 receptor agonists such as semaglutide and dual glucose-dependent insulinotropic polypeptide and glucagon-like peptide-1 receptor agonists such as tirzepatide are currently the best obesity drugs available." (PMID 39594522, 2024). "Similarly, other butyrogenic bacteria with probiotic properties, such as Butyricimonas virosa, are shown to ameliorate high-fat diet-induced obesity by activation of GLP-1R, improving glucose regulation and upregulated gut barrier tight junction proteins like zonula occludens-1." (PMID 37571301, 2023). "Furthermore, GLP-1R agonist treatment of HFD mice reversed obesity and insulin resistance." (PMID 33810265, 2021). "Therefore, improving the knowledge of the regulatory dynamics of the GLP1/GLP-1R axis in AT might have relevance for the treatment of local and systemic inflammatory events in obesity and T2D." (PMID 31000783, 2019). "To determine whether chronic i.c.v. exendin-4 infusion still leads to an increased uptake of plasma TG-derived fatty acids and glucose via BAT when obesity and insulin resistance have developed, we next explored the effects of central GLP-1R activation after 12 weeks of high-fat feeding." (PMID 26254578, 2015). "The current most common pharmaceutical interventions for obesity include orlistat, contrave, and GLP‐1 receptor (GLP‐1R) agonists like semaglutide." (PMID 41151834, 2026). "Glucagon-like peptide-1 receptor agonists (GLP-1RAs), particularly semaglutide, have emerged as highly effective therapies for T2DM and obesity." (PMID 41683613, 2026). "Glucagon-like peptide-1 receptor agonists (GLP-1RAs) are effective therapies for type 2 diabetes (T2D) and obesity, yet patient responses are variable, with GLP1R gene variation potentially linked to therapeutic outcomes." (PMID 41637494, 2026). "Metabolic (bariatric) surgery is an effective long-term intervention for obesity-related T2DM, while modern injectable pharmacotherapies, including glucagon-like peptide-1 receptor agonists, have become increasingly popular." (PMID 41835756, 2026). "Glucagon‐like peptide‐1 receptor (GLP‐1R) agonists (GLP‐1RAs) are highly effective for treating type 2 diabetes and obesity." (PMID 41017581, 2026). "Glucagon-like peptide-1 receptor agonists (GLP-1 RAs) are a commonly used class of antidiabetic medications in the treatment of type 2 diabetes mellitus and obesity management, and it is important to understand public awareness and attitudes toward GLP-1 RAs." (PMID 41517730, 2026). "Semaglutide, a glucagon-like peptide-1 receptor agonist (GLP-1), and tirzepatide, a dual glucose-dependent insulinotropic polypeptide and GLP-1 receptor agonist (GIP/GLP-1), are among the leading pharmacological options for obesity treatment." (PMID 41664890, 2026).
Obesity (continued). "GLP‐1R‐expressing cells within the dorsal vagal complex, containing the NTS and AP, are necessary for the weight‐reducing effects of GLP‐1‐based obesity drugs." (PMID 41017581, 2026). "Semaglutide is a glucagon-like peptide-1 receptor agonist (GLP-1 RA), primarily used as an antidiabetic and anti-obesity agent, which manifests pleiotropic effects through activation of GLP-1 receptors." (PMID 42205663, 2026). "Although the GIP and GIP receptor system is known to promote energy assimilation and contribute to obesity, the fact that a dual GIP/GLP-1R agonist exhibited stronger anti-obesity effects than GLP-1RAs alone was unexpected." (PMID 40607142, 2025). "Glucagon-like peptide-1 receptor agonists (GLP1-RAs) are considered promising treatment candidates for NAFLD and NASH and are indicated for the treatment of type 2 diabetes and obesity." (PMID 40939135, 2025). "From a therapeutic standpoint, the interaction between liraglutide and GLP-1R is crucial not only for its antidiabetic properties but also for its potential in treating conditions like nonalcoholic steatohepatitis (NASH) and obesity." (PMID 41226200, 2025). "Herein, we primarily focus on glucagon-like peptide-1 receptor agonists (GLP-1RAs) and their role in the management of CKD in the setting of overweight/obesity and T2DM." (PMID 40359159, 2025). "Glucagon-like peptide-1 receptor agonists (GLP-1RAs), such as semaglutide, approved for treating T2D and obesity, hold potential for MASH patients, offering cardiovascular benefits and MASH improvement." (PMID 40283580, 2025). "Other dual GLP-1R/GCGR agonists are being actively studied to treat NAFLD, with Pemvidutide (ALT-801) emerging as a promising candidate for managing obesity and MASH." (PMID 40004572, 2025). "Newer therapies, such as glucagon-like peptide 1 receptor agonists (GLP-1 RAs), have expanded the armamentarium of options for obesity management." (PMID 40755647, 2025). "The pursuit of orally bioavailable GLP-1R agonists represents a significant advancement in T2DM and obesity pharmacotherapy, aiming to replace the inconvenience of injectable incretin therapies." (PMID 41303737, 2025). "Glucagon-like peptide-1 receptor agonists are pivotal in managing T2DM and obesity, enhancing glycaemic control by boosting insulin secretion, reducing glucagon levels, delaying gastric emptying, and promoting satiety." (PMID 40708853, 2025). "Notably, the drugs Cotadutide, Survodutide, Efinopegdutide, Pemvidutide, and Bamadutide have been developed as GLP1-R/glucagon receptor agonists and can increase energy expenditure and decrease food intake and hepatic lipogenesis, counteracting the detrimental effects of obesity." (PMID 41155431, 2025). "Glucagon-like peptide-1 receptor agonists (GLP-1 RAs), approved for T2D and obesity, are now being explored for off-label use in individuals with T1D." (PMID 40022528, 2025). "As the first anti-obesity drug targeting multiple receptors, tirzepatide (Zepbound®, Eli Lilly), a dual GIPR/GLP-1R agonist, was approved by the FDA in 2022." (PMID 40607142, 2025). "A second GLP1R/GIPR coagonist, tirzepatide (previously called LY3298176, marketed as Mounjaro® for T2D and Zepbound® for obesity, Eli Lilly) is a 39-amino acid peptide acylated at the lysine 20 residue with a C20 fatty diacid." (PMID 40166681, 2025). "Since 2014, the pharmacological use of glucagon-like peptide-1 receptor agonists (GLP-1 RAs), which mimic the gut hormone GLP-1, has provided an alternative to lifestyle interventions for tackling obesity." (PMID 41328178, 2025). "Specifically, BMI-lowering relationships via GLP1R and GIPR loci appear to be predominantly mediated through CNS-driven behavioral regulation, influencing binge drinking, food preferences, and obesity." (PMID 40931165, 2025). "Tirzepatide, an imbalanced dual agonist of GLP‐1R/GIPR, has been approved for therapy in both T2D and obesity." (PMID 40838278, 2025).